EHBP1 (EH domain binding protein 1)
Description:
May play a role in actin reorganization. Links clathrin-mediated endocytosis to the actin cytoskeleton. May act as Rab effector protein and play a role in vesicle trafficking. Required for perinuclear sorting and insulin-regulated recycling of SLC2A4/GLUT4 in adipocytes (By similarity).
Synonyms: KIAA0903; NACSIN; HPC12
Tractability: Small molecule: a structure with a bound ligand is known. Antibody: its Gene Ontology location is reachable by antibodies, with high confidence; the Human Protein Atlas places it where antibodies can reach. PROTAC: ubiquitination databases record sites on it; its protein half-life has been measured.
Gene: Protein-coding gene on chromosome 2 (62,673,851 to 63,046,487, forward strand). Ensembl gene ENSG00000115504.
Subcellular location: Cytoplasm; Membrane; Endosome
Subcellular location (Human Protein Atlas): Plasma membrane; Cytosol
Gene Ontology:
Molecular function: actin filament binding; small GTPase binding
Biological process: actin cytoskeleton organization; endocytic recycling
Cellular component: cytosol; plasma membrane; cytoplasm; endosome; membrane
Genetic constraint (gnomAD): Loss-of-function variants: 49 observed, 111.68 expected, observed/expected ratio (o/e) 0.44, 90% interval 0.35 to 0.56. The upper end of that interval is the gene's LOEUF score, 0.56, which puts it in group 2 of 6, group 1 being the genes least tolerant of losing a copy. Missense variants: 1,111 observed, 1,276.1 expected, observed/expected ratio (o/e) 0.87, 90% interval 0.83 to 0.92. Synonymous variants: 435 observed, 451.59 expected, observed/expected ratio (o/e) 0.96, 90% interval 0.89 to 1.04.
Homologues: Orthologues: chimpanzee EHBP1 (99% identical), macaque EHBP1 (99% identical), dog EHBP1 (95% identical), pig EHBP1 (95% identical), rabbit EHBP1 (92% identical), mouse Ehbp1 (89% identical), rat Ehbp1 (89% identical), guinea pig EHBP1 (88% identical), tropical clawed frog ehbp1 (72% identical), zebrafish ehbp1 (66% identical), Drosophila melanogaster Ehbp1 (28% identical). Paralogues in human: EHBP1L1 (34% identical), ASPM (14% identical), MICALL1 (13% identical), MICALL2 (12% identical), GAS2L1 (6% identical), SMTNL1 (6% identical), GAS2 (3% identical).
Diseases named in the same sentence as EHBP1 in open-access papers:
EHBP1 is named in the same sentence as 28 diseases in open-access papers, as found by Europe PMC text mining. Sharing a sentence is not in itself a finding about the gene and the disease. The quoted sentences say what the papers report.
prostate carcinoma (12 papers, 2013 to 2025). A carcinoma that arises from epithelial cells of the prostate gland. "We identified a variant in the intron of the EHBP1 gene c.1185+30064G>A (rs721048) in 18 out of 72 prostate cancer patients, accounting for 25% of the total number of patients." (PMID 40004500, 2025). "We identified a pathological variant in the EHBP1 gene (rs721048) in 18 (25%) of Kazakh prostate cancer patients." (PMID 40004500, 2025). "We observed a more than two-fold increased risk of early-onset prostate cancer associated with higher EHBP1, an adaptor protein with a key role in vesicular trafficking and actin reorganization." (PMID 38878676, 2024). "Variants in the EHBP1 intron have previously been associated with aggressive prostate cancer in a genetic association study of Europeans and North Americans." (PMID 38878676, 2024). "The single nucleotide polymorphism rs721048(A>G) in EHBP1 is associated with an aggressive form of prostate cancer." (PMID 31552180, 2019). "For example, a genome-wide association study has linked EHBP1 to aggressive prostate cancer." (PMID 39664392, 2024). "A single‐nucleotide polymorphism in EHBP1 has been associated with an aggressive form of prostate cancer; it may be implicated in carcinogenesis or cell survival." (PMID 26432421, 2015). "Due to the observation of OTX1 and EHBP1 expression in various tumor tissues across cancer types, we hypothesized that the rs721048 variant, through enhancer activation, might increase the risk of malignancies beyond prostate cancer." (PMID 40004500, 2025). "Among men carrying two T alleles at rs2710647 in EH domain binding protein 1 (EHBP1) SNP, the risk of prostate cancer in those with high malathion use was 3.43 times those with no use (95% CI: 1.44–8.15) (P-interaction = 0.003)." (PMID 23593118, 2013). "Our data suggest that rs721048 may be associated with prostate cancer through the disruption of the mechanism of action of certain tumor-specific enhancers causing the dysregulation of the expression of OTX1 and EHBP1 genes." (PMID 35176995, 2022). "EHBP1 is also essential for the anti-invasive effect of atorvastatin in prostate cancer." (PMID 31552180, 2019). "An intron of EHBP1 is known to bear two SNPs that are associated with prostate cancer, but otherwise this gene has not previously been linked with cancer." (PMID 24324931, 2013). "However, the precise mechanism of EHBP1 in the onset and progression of prostate cancer are still unknown." (PMID 32295536, 2020).
dyslipidemia (2 papers, 2022 to 2024). "EHBP1 mutation and BMI were found to be independent risk factors for increased dyslipidemia risk in ESRD patients." (PMID 39731114, 2024). "This study demonstrated that the EHBP1 rs2710642G allele directly contributes to dyslipidemia and high TG levels in ESRD patients in Chinese Han population.." (PMID 39731114, 2024). "This study investigated the link between the EHBP1 single-nucleotide polymorphisms (SNPs) and dyslipidemia risks in maintenance dialysis patients with end-stage renal disease in Chinese Han population." (PMID 39731114, 2024). "One study suggested that the EHBP1 rs2710642 was linked to the odds of having dyslipidemia in ischemic stroke patients." (PMID 39731114, 2024). "Therefore, the current research explored how EHBP1 SNPs (rs2710642, rs2710642 and rs11688816), SNP–SNP interactions, and gene‒environment interactions were associated with dyslipidemia risks in ESRD patients in the Chinese Han population." (PMID 39731114, 2024). "It was previously reported that EHBP1 SNP–SNP and SNP–environment interactions are involved in the pathogenesis of dyslipidemia." (PMID 39731114, 2024). "Therefore, the study hypothesizes that mutations of lipid-related EHBP1 SNPs may result in different lipid phenotypes and these SNPs might interact with the environment to alter dyslipidemia risk; moreover, they might interact with PCSK9 to affect lipid levels." (PMID 39731114, 2024). "In this study, strong linkage disequilibrium was noted between the EHBP1 rs11688816 and rs2710642 in the control and dyslipidemia groups, as well as between the EHBP1 rs11688816 and rs2710642 in the control and high-TG groups." (PMID 39731114, 2024). "Haplotypes of EHBP1 rs2710642 and rs11688816, interactions between three SNPs (rs10496099, rs2710642, and rs11688816) and environmental factors (BMI, FBS, etc.)altered the risk of dyslipidemia in ESRD patients." (PMID 39731114, 2024). "Therefore, EHBP1 rs2710642G allele carried was a predict factor of dyslipidemia in ESRD patients in Chinese Han population, lose weight and BMI, and control their FBS might reduce their dyslipidemia risk." (PMID 39731114, 2024). "Second, it did not investigate how EHBP1 and dietary interactions influenced dyslipidemia risks in patients with ESRD." (PMID 39731114, 2024).
aneurysm (1 paper, 2021). Bulging or ballooning in an area of an artery secondary to arterial wall weakening. "Upon studying these genes for a possible role in MFS, four genes (FNBP1, EHBP1, SDK1, and PTPRN2) were found to be involved in cytoskeletal actin dynamics, which regulates cell-adhesion and cellular uptake or secretion, which is altered in MFS cells, and thought to play a role in aneurysm formation." (PMID 34895303, 2021).
atherosclerosis (1 paper, 2022). A disease characterized by the build-up of fatty material and calcium deposition in the arterial wall resulting in partial or complete occlusion of the arterial lumen. "Moreover, SNPs of the rs2710642 and rs10496099 in the EHBP1 were correlated with low-density lipoprotein cholesterol (LDL-C) and atherosclerosis, respectively." (PMID 35559044, 2022).
bladder cancer (1 paper, 2022). "We constructed a prognostic model based on Necroptosis subtype-related prognosis DEGS by lasso algorithm and multivariate COX analysis, which consists of 6 predictors (CERCAM POLR1H, KCNJ15, GSDMB, EHBP1, TRIM38), among which CERCAM is closely related to bladder cancer." (PMID 35478725, 2022).
colorectal cancer (1 paper, 2025). A primary or metastatic malignant neoplasm that affects the colon or rectum. "Among the colorectal cancer patients, 17 (14.2%) were found to have the c.1185+30064G>A variant in the EHBP1 gene; patients with other pathogenic variants in genes included in our panel were excluded." (PMID 40004500, 2025). "Alternative splicing regulated by the MYC family of transcription factors can be aberrant in colorectal cancer, affecting EHBP1 responsible for cellular organization in cancer cells." (PMID 40004500, 2025). "Increased expression of the EHBP1 gene tends to affect survival rates in patients with colorectal cancer (CRC), potentially via alterations to the response to neoadjuvant chemotherapy." (PMID 40004500, 2025).
coronary artery disease (1 paper, 2022). "The associations among the EH domain-binding protein 1 (EHBP1), tubulin beta class I (TUBB), and WW domain-containing oxidoreductase (WWOX) single nucleotide polymorphisms (SNPs) and coronary artery disease (CAD) and ischemic stroke (IS) are not yet understood." (PMID 35559044, 2022).
Crohn disease (1 paper, 2018). A gastrointestinal disorder characterized by chronic inflammation involving all layers of the intestinal wall, noncaseating granulomas affecting the intestinal wall and regional lymph nodes, and transmural fibrosis. "More interestingly, EHBP1 having been reported to associate Crohn’s disease in Ashkenazi Jewish was identified to relate the abundance of Bacteroidales." (PMID 30429843, 2018).
intrahepatic cholangiocarcinoma (1 paper, 2023). A carcinoma that arises from the intrahepatic bile duct epithelium in any site of the intrahepatic biliary tree. "In tumor research, an EHBP1-MET fusion was found in a patient with intrahepatic cholangiocarcinoma, increasing sensitivity to crizotinib." (PMID 37664112, 2023).
multiple sclerosis (1 paper, 2024). A progressive autoimmune disorder affecting the central nervous system resulting in demyelination. "Furthermore, our phenotype-wide association study highlighted genes like SLC39A8 and EHBP1’s associations with fluid intelligence and HFEs linked to multiple sclerosis and liver-related diseases." (PMID 38956042, 2024).
ZIKV infection (1 paper, 2020). "The results showed that ZIKV infection significantly increased OAS2, IFIT3 and IFITM1 levels, and decreased Clorf27, DLG1 and EHBP1 levels." (PMID 32276512, 2020).
cancer (7 papers, 2013 to 2025). A tumor composed of atypical neoplastic, often pleomorphic cells that invade other tissues. "Identifying EHBP1 c.1185+30064G>A among the male population of Kazakhstan will help form the high-risk groups for PC to prevent the development of malignant neoplasms." (PMID 40004500, 2025). "Nevertheless, EHBP1 has already been associated with cancer and is required for the insulin-mediated translocation of glucose transporter type 4." (PMID 34715892, 2021). "In the MPNST, aside from the NF1 mutation, other mutations in cancer‐associated genes such as EHBP1 and WNK3 were identified." (PMID 26432421, 2015). "In our study, a robust anoikis-related model was developed based on the expression levels of three genes: EHBP1, CSPG4, and PLOD1.The presence of these three genes has been linked to a variety of malignant tumors." (PMID 39664392, 2024). "Therefore, based on our findings, we conclude that the frequency of the pathogenic EHBP1 c.1185+30064G>A variant in Kazakh individuals without cancer is approximately 10%, which aligns with global population data." (PMID 40004500, 2025).
tumor (6 papers, 2022 to 2025). "In a case report involving a CCA patient with EHBP1-MET fusion, treatment with the MET inhibitor crizotinib led to a partial tumor response lasting 8 months." (PMID 38730642, 2024). "Finally, we used the ssGSEA method to determine the correlations between ANLN, POLR3G, EHBP1, and ERO1A and 24 types of tumor-infiltrating immune cells." (PMID 35769906, 2022).
infection (3 papers, 2021 to 2024). The state of being infected such as from the introduction of a foreign agent such as serum, vaccine, antigenic substance or organism. "Thus, the Rab10 effectors MICAL-L1 and EHBP1 impact Rab10+ tubules during infection by ΔsopD mutant bacteria." (PMID 34349110, 2021). "Here we show that EHBP1 and MICAL-L1 impact Rab10+ tubule regulation during infection and inhibit plasma membrane scission during infection by ΔsopD mutant bacteria." (PMID 34349110, 2021). "During infection, Rab10 and its effectors MICAL-L1 and EHBP1 are recruited to invasion sites." (PMID 34349110, 2021).
EHBP1 also shares sentences with these, for which no sentence is quoted: acute myeloid leukemia (2 papers); alcohol dependence (1); atrial septal defect (1); breast carcinoma (1); cryptorchidism (1); end-stage renal disease (1); hereditary prostate cancer (1); ischemic stroke (1); kidney stones (1); lung carcinoma (1); melanocytic neoplasm (1); melanoma (1); prostate adenocarcinoma (1); prostate tumour (1).